IGF2BP3 (insulin like growth factor 2 mRNA binding protein 3)
Diseases named in the same sentence as IGF2BP3 in open-access papers (continued):
Sharing a sentence is not in itself a finding about the gene and the disease.
hepatocellular carcinoma (56 papers, 2014 to 2026). A malignant tumor that arises from hepatocytes. "In hepatocellular carcinoma, 53 IGF2BP3‐associated alternative splicing events have been identified, suggesting that IGF2BP3 may promote hepatocellular carcinoma progression through alternative splicing events that enrich multiple oncologic pathways." (PMID 37850412, 2023). "For example, IGF2BP3 binds with m6A-modified circCCAR1 to improve its stability in hepatocellular carcinoma." (PMID 41318550, 2025). "In lenvatinib-resistant hepatocellular carcinoma, lactylation of IGF2BP3 at K76 promotes the generation of S-adenosylmethionine and induces RNA m6A modification, leading to drug resistance." (PMID 40994548, 2025). "IGF2BP3 K76la upregulates PCK2 expression in lenvatinib-resistant hepatocellular carcinoma cells, triggering serine metabolism reprogramming and conferring drug resistance." (PMID 40994548, 2025). "In hepatocellular carcinoma, IGF2BP3 stabilizes NRF2 mRNA to inhibit ferroptosis; whereas in lung adenocarcinoma, it modulates multiple anti-ferroptotic regulators such as GPX4, SLC3A2, ACSL3, and FTH1 to confer ferroptosis resistance." (PMID 40530014, 2025). "This study reveals that in lenvatinib‐resistant hepatocellular carcinoma, increased glycolysis results in lactate accumulation and lysine lactylation of IGF2BP3, which increase the expression of PCK2 and NRF2." (PMID 39450426, 2024). "Since IGF2BP3 recognizes m6A modification of Nrf2 mRNA and stabilizes it, IGF2BP3 knockdown significantly promotes ferroptosis of hepatocellular carcinoma cells after administration of sorafenib." (PMID 37714846, 2023). "In hepatocellular carcinoma, the expression of IGF2BP3 is correlated with advanced tumor stage/grade and metastasis." (PMID 36450891, 2023). "In hepatocellular carcinoma and glioblastoma, upregulation of IGF2BP3 increased c-Myc expression and activated PI3K-AKT pathway, thereby affecting cell proliferation, cell cycle, and apoptosis." (PMID 35615150, 2022). "For instance, the overexpression of IGF2BP3 is related to the aggressive phenotype in colon cancer, hepatocellular carcinoma, and nasopharyngeal carcinoma." (PMID 36313631, 2022). "IGF2BP3 was previously demonstrated to be an upstream regulator of AKT/mTOR signalling in hepatocellular carcinoma." (PMID 34894048, 2022). "IGF2BP3 reduced zonula occludens-1 (ZO-1) expression by facilitating the formation of a miR-191-5p-induced RISC in hepatocellular carcinoma cells." (PMID 34657141, 2021). "Consistent with a putative role in the maintenance of cellular stemness, IGF2BP3 expression is higher in triple-negative breast CSCs and hepatocellular carcinoma tumor-initiating stem-like cells than in the entire population of tumor cells." (PMID 32010687, 2019). "plants, has been demonstrated to inhibit IGF2BP3 expression and reduce the growth of hepatocellular carcinoma cells." (PMID 32010687, 2019). "In hepatocellular carcinoma, the IGF2BP3/AKT/mTOR pathway inactivates TGF-β signaling to maintain the expression of pluripotency genes along with the tumorigenesis and chemoresistance of CD133(+) stem cells." (PMID 32010687, 2019). "In lenvatinib-resistant hepatocellular carcinoma, proteomic analysis showed elevated lactylation modifications, especially IGF2BP3 K76la, which enhances serine metabolism reprogramming and m6A modification, improving antioxidant ability and lenvatinib resistance." (PMID 40994548, 2025). "It was found that the elevated expression of IGF2BP3 can foster the growth of hepatocellular carcinoma by regulating macrophage infiltration in the tumor microenvironment, promoting M2-type polarization, and inhibiting CD8+ T-cell activation, thus weakening the anti-tumor immune response." (PMID 40801655, 2025). "m6A reader insulin-like growth factor 2 mRNA binding protein 3 (IGF2BP3) may affect prognosis in hepatocellular carcinoma by modulating the TGF-β signaling pathway." (PMID 37434186, 2023).
hepatocellular carcinoma (continued). "Kaplan-Meier curves identified IGF2BP3 as having a prognostic value in hepatocellular carcinoma." (PMID 37234166, 2023). "The expression levels of SMG5, EZH2, ZNF239, and IGF2BP3 in different hepatocellular carcinomas were higher than those in the normal group in the Roessler Liver (34868_ at), Roessler Liver (203358_s_at), Roessler Liver (206261_at), and Roessler Liver (203819_s_at) studies." (PMID 33297932, 2020). "Interestingly, in a recent study, igf2bp3 was found to be among the list of genes that were found to have a lower expression in cirrhosis samples when compared to hepatocellular carcinoma tissues." (PMID 24548546, 2014). "In hepatocellular carcinoma (HCC), IGF2BP3 prevents ferroptosis following sorafenib treatment by modifying m6A and increasing the stability of NRF2 mRNA, which is closely linked to tumor growth and poor prognosis in HCC." (PMID 40271153, 2025). "The reciprocal regulation of tumor-initiating stem-like cells by TLR4, and TGF-β requires YAP1 and IGF2BP3 in hepatocellular carcinoma (HCC)." (PMID 29312609, 2017). "It has the potential to induce ferroptosis in colorectal cancer and hepatocellular carcinoma by elevating the levels of ROS and SOD, while downregulating GPX4, GSH, and IGF2BP3." (PMID 41465430, 2025). "In hepatocellular carcinoma, m6A methylation of vascular endothelial growth factor A (VEGFA) mRNA was modified by methyltransferase RBM15 and two readers, YTHDF2 and IGF2BP3." (PMID 41272900, 2025). "Although O-GlcNAcylation of METTL3 had minimal effect on its subcellular localization and methyltransferase activity, it enhanced its interaction with WTAP, thereby sustaining m6A levels in hepatoma cells and stabilizing MCM10 mRNA via IGF2BP3." (PMID 40651967, 2025). "RIP-qPCR analysis confirmed a direct interaction between IGF2BP3 and MCM10 mRNA in hepatoma cells, with METTL3-WT interacting stronger than METTL3-3A." (PMID 40651967, 2025). "Notably, studies in hepatocellular carcinoma, prostate cancer, melanoma, and lung cancer have demonstrated how lactylation drives specific resistance phenotypes, such as stabilizing Insulin-like Growth Factor 2 mRNA-Binding Protein 3 (IGF2BP3), promoting Wnt/β-catenin signaling, or expanding Tregs." (PMID 41179284, 2025). "USP16 also deubiquitinates proteins in oncogenic pathways, for example, IGF2BP3 in gallbladder cancer, whereas Ct-HBx inhibits the expression level of USP16 in hepatocellular carcinoma, revealing the intrinsic link to cancer development." (PMID 36980227, 2023). "Specifically, previous evidence has indicated that IGF2BP3 plays a crucial role in human cancer development, such as breast cancer, mesothelioma, colon cancer, lung cancer, melanoma, nasopharyngeal carcinoma (NPC), and hepatocellular carcinoma (HCC)." (PMID 36761737, 2023). "IGF2BP3 could promote the interaction between LINC01138 and PRMT5 by combining with LINC01138 and ultimately increase PRMT5 stability in hepatocellular carcinoma." (PMID 35676262, 2022). "Similarly, studies have also reported the tumor-promoting role of IGF2BP1, IGF2BP3, IGFBP6 and IGFL2 in several cancers such as hepatocellular carcinoma, pancreatic and prostate cancers." (PMID 34061869, 2021). "In hepatocellular carcinoma (HCC), the m6A‐modified circRAPGEF1 destabilizes ASS1 mRNA via competitive binding to IGF2BP3, driving aspartate metabolic reprogramming in liver cancer stem cells (LCSCs)." (PMID 40801445, 2025). "Upon lactification, Insulin-like Growth Factor 2 mRNA-Binding Protein 3 (IGF2BP3) stabilizes both PCK2 and NRF2 mRNA, augments the activity of the antioxidant system, and bolsters the resistance of hepatocellular carcinoma (HCC) to lenvatinib." (PMID 41179284, 2025). "Similarly, IGF2BP3 overexpression de-sensitized sorafenib and doxorubicin by enhancing cancer stem cell marker CD133 and drug efflux proteins such as ABCB1 and ABCG2 in human hepatocellular carcinoma." (PMID 38328550, 2024).
hepatocellular carcinoma (continued). "However, the biological functional analysis of IGF2BP3 in hepatocellular carcinoma (HCC) and pan-cancer is not comprehensive." (PMID 38577615, 2024). "In hepatocellular carcinoma (HCC), the cancer-testis lncRNA-CTHCC promotes HCC growth and metastasis, and mechanistically, lncRNA-CTHCC is modified by m6A methylation with METTL3 and IGF2BP1/IGF2BP3 to maintain its stability and increase its expression." (PMID 35541906, 2022).
pancreatic cancer (45 papers, 2010 to 2026). "We found that among the numerous m6A-associated genes, IGF2BP3, an m6A-reading protein, had the most significant increase, which was consistent with the protein levels in pancreatic cancer." (PMID 41285728, 2025). "IGF2BP3 was initially identified as a highly expressed gene in pancreatic cancer, and the encoded protein was then confirmed to be an m6A reader." (PMID 37298373, 2023). "We also analyzed the expression of m6A readers in pancreatic cancer tissues from the TCGA database, and the expression of IGF2BP3 was associated with the prognosis of pancreatic cancer." (PMID 36276112, 2022). "An in-depth study of m6A regulators showed that IGF2BP3 is tightly associated with the occurrence and development of pancreatic cancer." (PMID 35136045, 2022). "In the LinkedOmics dataset, the high expression of IGF2BP1, IGF2BP2, and IGF2BP3 was significantly associated with the poor overall survival of pancreatic cancer patients." (PMID 33246429, 2020). "Further analysis confirmed that only IGF2BP2 and IGF2BP3 were associated with pancreatic cancer progression." (PMID 33246429, 2020). "IGF2BP3 imbalance-induced pancreatic cancer may be related to pathogenic E. coli infection." (PMID 33246429, 2020). "In 1997, IGF2BP3 was discovered in a large-scale screen for differentially expressed genes in pancreatic cancer, and it was cloned and initially named as a KH domain-containing protein overexpressed in cancer (KOC)." (PMID 40427100, 2025). "Mechanistically, pancreatic cancer cell‐derived EVs mediate linc‐ZNF25‐1 to promote Asn uptake via the IGF2BP3/c‐Myc/SLC1A5 pathway in PSCs." (PMID 40041969, 2025). "Then, the correlation of IGF2BP3, EMP1, and VASP expression was analyzed in the TCGA-PAAD data cells, and results revealed that the expression of EMP1 or IGF2BP3 was positively correlated with VASP in pancreatic cancer." (PMID 41285728, 2025). "Depletion of EMP1 also severely impaired the metastatic colonization of pancreatic cancer cells, overexpressing IGF2BP3 in mice lung tissue when tumor cells were injected via the tail vein in nude mice." (PMID 41285728, 2025). "For further validation, an RNA immunoprecipitation (RIP) assay using an anti‐IGF2BP3 antibody was performed on PSCs treated with EVs from pancreatic cancer cells." (PMID 40041969, 2025). "We identified that when IGF2BP3 expression was suppressed, the skeleton synthesis in pancreatic cancer cells was inhibited." (PMID 41285728, 2025). "IGF2BP3 overexpression in pancreatic cancer cells promoted the activation of the TGF-β signaling pathway." (PMID 41285728, 2025). "As expected, subcutaneous xenograft tumors of pancreatic cancer cells overexpressing IGF2BP3 revealed significantly enhanced tumor proliferation in vivo." (PMID 41285728, 2025). "Subsequently, the Kyoto encyclopedia of genes and genomes (KEGG) functional enrichment analysis differential genes of RNA-seq data from pancreatic cancer cells with IGF2BP3 knockdown revealed that the TGF-β/Smads signaling pathway was predominantly affected." (PMID 41285728, 2025). "A subsequent assay of proteins from pancreatic cancer tissue samples and cell samples once again corroborated the effect of IGF2BP3 on TGF-β/Smads pathway activation." (PMID 41285728, 2025). "The protein level of IGF2BP3 was evaluated by IHC in pancreatic cancer tissue microarrays (Cohort1)." (PMID 41285728, 2025). "The influence of IGF2BP3 in the invasive capacity of pancreatic cancer cells still lacks in-depth studies." (PMID 41285728, 2025). "Among the m6A-regulated molecules, IGF2BP3 was the most significantly elevated and promoted pancreatic cancer cell invasion and proliferation by affecting the transforming growth factor-β (TGF-β) signaling pathway." (PMID 41285728, 2025). "We observed that IGF2BP3 promoted proliferation in vivo and metastatic invasive ability in pancreatic cancer." (PMID 41285728, 2025).
pancreatic cancer (continued). "This dataset was obtained by performing RIP-seq of IGF2BP3 using an anti-IGF2BP3 antibody or normal rabbit IgG in extracts from the fibronectin-stimulated pancreatic cancer cell line." (PMID 38760723, 2024). "As a m6A reader, IGF2BP3 was first reported in 1997 due to its high expression in pancreatic carcinoma." (PMID 36761737, 2023). "Through the GEO database, it was found that expression of METTL3 and IGF2BP3 in pancreatic cancer tissues were higher than those in adjacent tissues." (PMID 36276112, 2022). "In the migration and invasion experiments, interfering with the expression of METTL3 and IGF2BP3 inhibited the migration and invasion of pancreatic cancer." (PMID 36276112, 2022). "To further explore the role of METTL3 and IGF2BP3 in pancreatic cancer, we conducted western blot experiments by transfecting METTL3-siRNA and IGF2BP3-siRNA into PANC-1 and Mia-Paca2." (PMID 36276112, 2022). "Through further exploration, we found that METTL3 and IGF2BP3 can significantly inhibit the migration and invasion of pancreatic cancer cells." (PMID 36276112, 2022). "In pancreatic cancer, the DNA methylation level of IGF2BP3 is significantly reduced, and the expression level of IGF2BP3 is increased, which is related to the poor overall survival of patients." (PMID 35047058, 2022). "The promotion function by METTL14 in pancreatic cancer was uncovered and IGF2BP3 was found to be a potential prognosis marker and therapeutic target of colon cancer." (PMID 33718187, 2021). "IGF2BP2 and IGF2BP3 are key factors in promoting the progression of pancreatic cancer and are closely related to overall survival." (PMID 33246429, 2020). "Regarding IGF2BP3, all four pancreatic cancer datasets indicated overexpression in both pancreatic carcinoma and pancreatic ductal adenocarcinoma." (PMID 33246429, 2020). "IGF2BP2 and IGF2BP3, which are related to pancreatic cancer progression and survival, were further analysed, and their functions were verified in vitro." (PMID 33246429, 2020). "Among the family members, the expression levels of IGF2BP2 and IGF2BP3 were significantly increased in pancreatic cancer tissues." (PMID 33246429, 2020). "The upregulation of IGF2BP3 expression in pancreatic cancer tissues supports research on this pathway." (PMID 33246429, 2020). "Further clinical correlation analysis of IGF2BP2 and IGF2BP3 confirmed that IGF2BP2 and IGF2BP3 are fundamental factors in promoting pancreatic cancer progression." (PMID 33246429, 2020). "Although we explored the mutation types and possible carcinogenic mechanisms of IGF2BP2 and IGF2BP3 in pancreatic cancer, the mechanisms that promote the progression of pancreatic cancer need further study." (PMID 33246429, 2020). "As predicted in the GSEA above, we inferred that IGF2BP2 and IGF2BP3 promote the proliferation or metastasis of pancreatic cancer cells to accelerate progression." (PMID 33246429, 2020). "Both IGF2BP2 and IGF2BP3 have great potential to become biomarkers for pancreatic cancer, as verified in patients." (PMID 33246429, 2020). "In pancreatic cancer, the DNA methylation level of IGF2BP3 is significantly reduced and the expression IGF2BP3 is higher, associated with patient overall survival." (PMID 31801551, 2019). "In pancreatic cancers, IGF2BP3 promotes the invasiveness and metastasis of the cancer cells through locally translated IGF2BP3-bound transcripts." (PMID 32083017, 2019). "In pancreatic cancer cells, IGF2BP3 and IGF2BP3-bound transcripts, including ARF6 and ARGHEF4, accumulate in membrane protrusions." (PMID 32010687, 2019). "We show evidence that IGF2BP3 and IGF2BP3-bound transcripts are localized in cytoplasmic RNA granules that accumulate in membrane protrusions of pancreatic cancer cells." (PMID 25216519, 2014). "Here, we report that IGF2BP3 promoted the invasiveness and metastasis of pancreatic cancers through locally translated IGF2BP3-bound transcripts." (PMID 25216519, 2014).